ZNF439 (zinc finger protein 439)
Description:
May be involved in transcriptional regulation.
Synonyms: DKFZp571K0837
Tractability: PROTAC: ubiquitination databases record sites on it.
Gene: Protein-coding gene on chromosome 19 (11,848,726 to 11,883,750, forward strand). Ensembl gene ENSG00000171291.
Subcellular location: Nucleus
Subcellular location (Human Protein Atlas): Nucleoplasm
Pathways (Reactome):
Gene expression (Transcription): Generic Transcription Pathway
Gene Ontology:
Molecular function: protein binding; DNA-binding transcription factor activity, RNA polymerase II-specific; RNA polymerase II transcription regulatory region sequence-specific DNA binding
Biological process: regulation of transcription by RNA polymerase II; regulation of DNA-templated transcription
Cellular component: nucleus
Genetic constraint (gnomAD): Loss-of-function variants: 40 observed, 49.06 expected, observed/expected ratio (o/e) 0.82, 90% interval 0.63 to 1.06. The upper end of that interval is the gene's LOEUF score, 1.06, which puts it in group 4 of 6, group 1 being the genes least tolerant of losing a copy. Missense variants: 556 observed, 622.06 expected, observed/expected ratio (o/e) 0.89, 90% interval 0.83 to 0.96. Synonymous variants: 171 observed, 203.79 expected, observed/expected ratio (o/e) 0.84, 90% interval 0.74 to 0.95.
Homologues: Orthologues: chimpanzee ZNF439 (94% identical), mouse Zfp78 (35% identical), Drosophila melanogaster CG3281 (23% identical), Drosophila melanogaster CG2712 (21% identical), Drosophila melanogaster Phs (19% identical). Paralogues in human: ZNF69 (82% identical), ZNF440 (79% identical), ZNF763 (61% identical), ZNF20 (56% identical), ZNF491 (53% identical), ZNF555 (45% identical), ZNF77 (42% identical), ZFP90 (39% identical), ZNF124 (38% identical), ZNF266 (38% identical), ZNF404 (38% identical), ZNF560 (38% identical), and 50 more.
Diseases named in the same sentence as ZNF439 in open-access papers:
ZNF439 is named in the same sentence as 1 disease in open-access papers, as found by Europe PMC text mining. Sharing a sentence is not in itself a finding about the gene and the disease. The quoted sentences say what the papers report.
tumor (2 papers, 2016 to 2025). "The results showed that CCR7, KMO, IF57, and HDAC9 were highly expressed in HNSCC tumor tissues, while ZNF439 was highly expressed in normal tissues." (PMID 40145017, 2025). "Analysis of the expression of the TILB-related signature genes in B Plasma cells showed that KMO, IFT57, HDAC9, GSAP, and CCR7 were significantly highly expressed in tumor tissue, while ZNF439 and KDM5D showed a similar trend." (PMID 40145017, 2025). "The results showed that ZNF439 and KDM5D were highly expressed in normal tissues, whereas KMO, FT57, HDAC9, GSAP, and CCR7 were highly expressed in tumor tissues." (PMID 40145017, 2025). "Lastly, in the young.tumor versus old.tumor contrast, we identified five DEGs (ZIC2, ZIC5, ZNF439, USP54, and C2); this contrast may reflect differences in intrinsic tumor properties between tumors from the two age cohorts." (PMID 28027300, 2016).